BRCA1 (BRCA1 DNA repair associated)
Diseases named in the same sentence as BRCA1 in open-access papers (continued):
Sharing a sentence is not in itself a finding about the gene and the disease.
cancer (continued). "Because our data lead to tempering the reliability of basing individualization of the starting age of preventive measures on family history, they also emphasize the need for refining the understanding of phenotype variability of BRCA1/2 cancer-susceptibility hereditary syndrome." (PMID 34356116, 2021). "Furthermore, BRCA1/2 mutated cancers exhibit an increase in large-scale state transition (LST) score, which is reflective of large rearrangements, but HPV+ HNSCC genomes do not exhibit this hallmark, either." (PMID 34696429, 2021). "However, the potential impact of BRCA1 mutation on the individual cell populations within a tumor microenvironment, and its relation to increased aggressiveness of cancer is not well understood." (PMID 35008272, 2021). "Although the majority of BRCA1-deficient cancer patients respond to DNA-damaging agents such as cisplatin and poly (ADP-ribose) polymerase (PARP) inhibitors, tumor recurrence and resistance, likely driven by TICs, combine to decrease the 5-year survival of such patients." (PMID 33478572, 2021). "However, BRCA1-mutated cancers have been found to develop resistance to cisplatin treatment through a secondary mutation that re-establishes BRCA1 function." (PMID 34360968, 2021). "While many BRCA1-associated cancers undergo LOH for the wildtype BRCA1 allele, many acquire other genomic ‘hits’ prior to this event, which may be required for subsequent LOH." (PMID 32527287, 2020). "Interestingly, a distinctive clinical phenotype has been reported in association with HR-deficient cancers, especially those characterized by BRCA1/2 mutations." (PMID 32455819, 2020). "A homologue of the breast cancer susceptibility gene (BRCA1) was also identified on chromosome 1B." (PMID 33370360, 2020). "Three relatives of a cancer patient (P24) were found to have the same pathogenic mutation in in BRCA1 (c.5098delC) gene as the patient, and thus they might show symptoms of HBOC in future." (PMID 33552952, 2020). "Further studies are needed to determine whether the global genomic instability features of BRCA1/BRCA2-associated cancer are related to estrogen-induced DNA damage." (PMID 33299637, 2020). "However, Vos and colleagues suggest that there are reasons to handle information about VUS carefully as nearly 80% of patients with VUS in BRCA1/2 believed that this finding was connected with a slightly high risk for cancer." (PMID 33087101, 2020). "Furthermore, we characterize the penetrance of cancer in carriers of pathogenic BRCA1 and BRCA2 variants." (PMID 33087929, 2020). "Further investigation of this population and FCH of related cancers may uncover candidates with high potential for BRCA1/2 mutations." (PMID 33351846, 2020). "Nonetheless, our findings guide researchers to focus on issues raised by BRCA1/2 PV/LPV carriers that may pose as barriers in maximizing their cancer risk management options that arise with the knowledge of their BRCA1/2 status." (PMID 33110458, 2020). "Although germline and somatic variants of BRCA1/2 have been described, variants in their genetic regions only account for a small proportion of cancer risk, and the majority is currently unknown, which remains a difficulty for genetic testing." (PMID 31998560, 2020). "Furthermore, a number of prediction models have been developed to assess the likelihood of a BRCA1/2 variant detection, mainly by taking into consideration the family cancer history of an affected individual." (PMID 32727387, 2020). "Also, different splicing variants of BRCA1, a well know cancer susceptibility gene, modulate DNA repair mechanisms, and the BRCA1 protein has been shown to be a regulator of the splicing process, affecting the expression of repair factors." (PMID 32236390, 2020). "Therefore, it is important to consider how BRCA1/2-deficient tumors are being treated as the vast majority of patients currently targeted with a synthetic lethal approach have BRCA-mutated cancers." (PMID 33015624, 2020).
cancer (continued). "This suggests that the effect size of BARD1 c.1670G>C; p.Cys557Ser could be small, that is, it could confer a low–moderate risk to cancer relative to the high risk associated with BRCA1/BRCA2 pathogenic variants." (PMID 32726901, 2020). "At those loci, BRCA1 mutated cancers show accumulation of insertions or deletions." (PMID 32098397, 2020). "However, the role of BRCA1/2-associated family cancer history (FCH) has remained unexplored in treating these four cancer types as a homogenous pathophysiological group." (PMID 33351846, 2020). "Because BRCA1 plays a critical role in DNA end resection and RAD51 loading, BRCA1-mutated cancers are unable to effectively carry out HR repair and rely on alternative pathways, such as non-homologous end joining (NHEJ), single-strand annealing (SSA) and microhomology-mediated end joining (MMEJ)." (PMID 32182354, 2020). "POLQ overexpression has also been observed in cancers with BRCA1/BRCA2 mutation, suggesting that it may represent an adaptive response to elevated replication-associated DSB burden, although the precise mechanism of upregulation remains to be elucidated." (PMID 33385162, 2020). "Dysfunction of wild type BRCA1 protein also associates with cancer, but its mechanism is unclear." (PMID 32655836, 2020). "40–50% more individuals with mutations in these cancer susceptibility genes could be identified by multigene panel testing as compared to testing for BRCA1 and BRCA2 genes only." (PMID 33552952, 2020). "As a consequence, treating BRCA1/2-deficient HGSOCs by trying to restore BRCA1/2 function could represent an ineffective strategy and might render these cancers even more fit." (PMID 32455819, 2020). "Therefore, the defective FA pathway leads to cancer predisposition through genetic instability, such as BRCA1 and BRCA2 dysfunction." (PMID 32269964, 2020). "Indeed, pathogenic variants often represent only a small percentage (< 20%) of all the variants established in high risk cancer genes, such as BRCA1/2." (PMID 32127026, 2020). "Indeed, interruption of the menstrual cycle by either pregnancy or oral contraceptive use has a profound effect on the life-time risk of these cancers not only in the general population, but also in BRCA1 mutation carriers." (PMID 32120796, 2020). "Additionally, BRCA1/BRCA2-mutated cancer carried microhomology-mediated deletions more frequently compared with the wild-type cancers." (PMID 32269964, 2020). "This review aims to give an overview of available screening guidelines for female and male carriers of pathogenic or likely pathogenic germline BRCA1/2 variants per cancer type, incorporating malignancies that are more or less recently well correlated with BRCA1/2." (PMID 32655641, 2020). "PARPi have been shown to effectively kill cancer cells harboring gene mutations in BRCA1 and BRCA2." (PMID 32784607, 2020). "Moreover, HPV proteins, especially E6 and E7, are able to interact with breast and ovarian cancer susceptibility gene-1 (BRCA1) and BRCA2 that are tumor suppressors agents." (PMID 32458652, 2020). "Twenty-four (5.07%) patients had more than three first-degree relatives affected by BRCA1/2-associated cancer (group A), two (0.42%) patients had three successive generations of BRCA1/2-associated FCH (group B), and five (1.06%) patients had two relatives diagnosed < 55 years of age (group C)." (PMID 33351846, 2020). "Analysis of affected individuals belonging to high‐risk pedigrees has long been a powerful design for identification of rare cancer predisposition genes and variants in Utah (e.g., BRCA1 [OMIM 113705], BRCA2 [OMIM 600185], CDKN2A [OMIM 600160], GOLM1 [OMIM 606804], APC, PTEN [OMIM 601728])." (PMID 33118316, 2020).
cancer (continued). "In cancer cells with BRCA1/2 mutations or other HRDs, the inhibition of PARP results in a synthetic lethal interaction as the accumulation of double-strand breaks coupled with inadequate repair mechanisms can lead to chromosomal instability, cell cycle arrest and subsequent apoptosis." (PMID 33036656, 2020). "In addition, previous genome profiling study against advanced cancers indicated that more than 75% of pathogenic BRCA1/2 variants identified in tumors were originated from germline variants." (PMID 31628423, 2020). "Moreover, even PARPi-resistant BRCA1-deficient cancer cells are sensitive to ATR inhibition, in part due to the role of ATR in supporting BRCA1-independent loading of RAD51." (PMID 32015826, 2020). "We do acknowledge that there may be underestimation of HRD frequency in these other cancer types due to the low prevalence of BRCA1/2 deficient samples, which served as examples of HRD samples for training CHORD." (PMID 33149131, 2020). "We found that BRCA1/2-associated FCH was potentially related to early-stage cancer." (PMID 33351846, 2020). "This suggests that guidelines such as NCCN may exclude from testing a significant number of women with mutations in cancer predisposition genes other than BRCA1 and BRCA2." (PMID 31963545, 2020). "Further analysis of the mechanisms in nutlin-3a-induced PARP1 degradation may lead to the development of novel PARP1 suppressors applicable for cancers with BRCA1 mutation." (PMID 32405340, 2020). "Interestingly, several of the human cancer predisposition genes have been discovered in the constitutional (germline) DNA of dogs with cancer, including mutations in BRCA1, BRCA2, and p5321–24." (PMID 32005926, 2020). "Inhibition of PARPs has been implemented in the treatment of BRCA1/2 mutated cancers." (PMID 32708251, 2020). "Little was known about the biological function of BRCA1 when it was first reported as a cancer predisposing gene other than the predicted loss-of-function variants suggested that it may behave as tumour suppressor gene." (PMID 32726901, 2020). "Importantly, BRCA1 deficiency can be induced by epigenetic silencing through promoter hypermethylation, which is a leading cause of BRCA1-defective cancer." (PMID 33324554, 2020). "However, BRCA1 or BRCA2-null cancer cells are deficient in HR and the problems caused by PARP inhibition become lethal even in the absence of exogenous genotoxic stress." (PMID 32029902, 2020). "Point mutations that disrupt BRCA1 sequestration by BRCA1-A have been identified in human cancer patients: A mutation in the nuclear localization sequence of ABRAXAS (R361Q) results in a completely assembled, functional BRCA1-A complex that is excluded from the nucleus." (PMID 33142801, 2020). "Furthermore, there was a significantly higher EZH2 mRNA expression in cancers with confirmed BRCA1 mutations (P = 0.013)." (PMID 33230143, 2020). "Interestingly, the de novo BRCA1/2 mutations described in the literature have typically been identified in patients with early-onset cancer, possibly reflecting selection bias." (PMID 32468491, 2020). "Using cancer incidence as an endpoint for cancer prevention trials targeting BRCA1 mutation carriers may raise ethical concerns due to unrealistically long study periods or prohibitive costs." (PMID 32120796, 2020). "This allele has also been used to generate tissue-specific BRCA1 null cancer models." (PMID 32257107, 2020). "As a consequence, the differences in absolute risk become larger when the PRS is considered together with family history or variant location and demonstrate that the PRS should be considered in combination with other risk factors to provide comprehensive cancer risks for BRCA1/2 carriers." (PMID 32665703, 2020). "The identification of BRCA1/2-pathogenic variants is imperative and could directly impact on prevention, early cancer diagnosis, and clinical management of patients." (PMID 32087690, 2020).
cancer (continued). "Other primary cancers were also slightly more common in BRCA1/2 mutation carriers (16.5% vs 9.5%)." (PMID 32322271, 2020). "Notably, 20% of tumors from a pan-cancer analysis identified subclonal mutations in the BRCA1/2 pathway." (PMID 32974031, 2020). "In addition, 30 (5.72%) patients carried a total of 38 LP/P mutations in other cancer susceptibility genes beyond BRCA1/2." (PMID 32091409, 2020). "The goal of achieving the highest degree of cancer risk reduction is the primary driver for women with BRCA1 or BRCA2 mutations in selecting an intervention and a sequence of interventions, regardless of whether it is non-surgical or surgical." (PMID 33014209, 2020). "This has already been demonstrated in BRCA1/2 mutation-carrier cancer patients." (PMID 32211398, 2020). "The resulting genomic instability (chromosomal translocations and deletions) and mutations may be the underlying mechanism of BRCA1/2 associated cancers." (PMID 31197228, 2020). "BRCA1/2 germline mutation related cancers are candidates for new immune therapeutic interventions." (PMID 32164626, 2020). "BRCA1: p.Ile1845fs variant carriers were more likely to have family history of cancer (P = 0.034)." (PMID 31908633, 2020). "This proved to be crucial in analyses of the cancer risk associated with mosaic BRCA1 methylation." (PMID 32859265, 2020). "However, the expression levels of breast cancer susceptibility gene 1 (BRCA1), a cancer-inhibiting gene related to NF-κB inhibition, were decreased following irinotecan treatment (p < 0.05)." (PMID 32927892, 2020). "The higher incidence of basal-like cancers in very young women may be associated with an increase in the expression of BRCA1 mutations, luminal progenitors, and c-kit in younger patients." (PMID 31739537, 2019). "Identification of the BRCA1 gene 25 years ago revolutionized the field of cancer risk assessment." (PMID 31379942, 2019). "Improving collection of health history information for both individuals and providers could improve prevention efforts for individuals at risk of BRCA1/2-related cancers." (PMID 31083288, 2019). "Additionally, the association between carry the 9–12 deletion BRCA1 with different clinical features such as age at diagnosis, type of cancer, tumor phenotype, was analyzed among patients, carriers and non-carriers." (PMID 31545835, 2019). "Furthermore, approximately 10–15% of TNBC tumours carry hereditary mutations in the BReast CAncer early onset 1 and 2 genes (BRCA1/2 genes), which are responsible for hereditary predisposed cancers developments." (PMID 31888054, 2019). "Interestingly, tumors with defective HR, including BRCA1/2 mutation cancers, exhibit particular sensitivity to PARP inhibitors." (PMID 30717758, 2019). "It is important as the type and location of a particular mutation may alter the cancer risk estimate, as was previously shown for BRCA1/2 mutations." (PMID 31142030, 2019). "The small number of old cancer-free BRCA1 mutation carriers was a limiting factor in this study." (PMID 31395037, 2019). "In the same population the mutation of BRCA1 gene varies according to the age of onset of cancer." (PMID 31759379, 2019). "Cancer therapies using defects in homologous recombination (HR) DNA repair pathway of tumor cells are not yet approved to be applicable in patients with malignancies other than BRCA1/2-mutated tumors." (PMID 31423128, 2019). "PARP inhibitors are mainly used to treat BRCA1/2 mutated cancers." (PMID 31266951, 2019). "Variants whose impact on function cannot be directly inferred by the genetic code are categorized as VUS and are evaluated by multifactorial likelihood models that use personal and family history of cancer, segregation data, prediction tools, and co-occurrence with a pathogenic BRCA1 variant." (PMID 31013702, 2019).
cancer (continued). "However, inhibiting both pathways, represented by administration of PARP inhibitors in BRCA1/2-mutated cancers, prevents both DNA repair machineries, resulting in unrepairable DNA damage and subsequent cell death of the mutated cancer cells." (PMID 30813388, 2019). "However, for some cancer cells with HR deficiency such as BRCA1/2 mutations, NHEJ pathway is utilized for DSB repair." (PMID 31521196, 2019). "In addition, the classification we used for familial cancer risk (low, medium, and high) was based on self-reported family history for BRCA1/2-related cancers." (PMID 31083288, 2019). "Regarding the expression of the evaluated cytokeratins, the cancers associated with a germline pathogenic variant in BRCA1 were more frequently positive for CK5/6 and CK14 than tumors associated with a germline pathogenic variant in BRCA2 (p = 0.031 and p = 0.008, respectively)." (PMID 31244284, 2019). "Pathogenic variants in BRCA1 and BRCA2 (BRCA1/2) lead to increased risk of breast, ovarian, and other cancers, but most variant-positive individuals in the general population are unaware of their risk, and little is known about prevalence in non-European populations." (PMID 31892343, 2019). "The compound could be further investigated as a promising tool for targeted therapy of cancer cells with deficiencies in BRCA1/2-based HR-pathway." (PMID 31615159, 2019). "Importantly, the batch effect causes substantial differences in germline variant distribution patterns across numerous genes, including prominent cancer predisposition genes such as BRCA1, RET, MAX, and KRAS." (PMID 31391007, 2019). "By increasing uptake of BSO and breast MRI, cancer incidence and mortality in women with a BRCA1 or BRCA2 mutation could be reduced." (PMID 30971774, 2019). "In addition to BRCA1/ 2, many other genes encoding HR enzymes are involved in both inherited and acquired cancers and have been associated with PARP inhibitor sensitivity when deficient in vitro or in vivo." (PMID 31159747, 2019). "This is of special importance for the analysis of DDR-genes such as BRCA1/2, since cancer-predisposing loss-of-function mutations may occur at any position in the gene." (PMID 31029168, 2019). "The cancer types commonly considered important for risk assessment are breast (female and male), ovarian, prostate, and pancreatic cancer, all of which are included in the BOADICEA model predicting risk of cancer for BRCA1 and BRCA2 pathogenic variant carriers." (PMID 31131967, 2019). "In addition, RD‐N synergistically increased cell sensitivity to cisplatin, and this effect was more evidenced in BRCA1‐deficient cancer cells." (PMID 30565390, 2019). "BRCA1/2 is one of the most frequently studied cancer predisposition genes." (PMID 31132991, 2019). "Approximately 15–20% of HGSOCs may be inherited with the most common germline mutations related to alterations in breast cancer 1 (BRCA1) and breast cancer 2 (BRCA2) genes." (PMID 30909618, 2019). "Furthermore, BRCA1 is a relatively large gene and its protein product has three representative domains, frequently mutated in cancer patients with relatively high frequency." (PMID 31064392, 2019). "The classification of missense germline variants in the BRCA1/2 genes as pathogenic could have a significant impact on the evaluation of cancer risk." (PMID 31569370, 2019). "Cancers with mutation of BRCA1/2 are treatable by PARP inhibitors." (PMID 30813388, 2019).